AR (androgen receptor)
Diseases named in the same sentence as AR in open-access papers (continued):
Sharing a sentence is not in itself a finding about the gene and the disease.
breast carcinoma (continued). "Like PR, the activation of AR in ER+ breast cancer exerts anti-tumorigenic activity by reprogramming the ER cistrome and enhancing responsiveness to endocrine therapy." (PMID 41261233, 2026). "In a subset of hormone receptor–positive prostate and breast cancers, this therapeutic combination degraded AR and ER, respectively, and led to cell death." (PMID 41295982, 2026). "This scoping review provides a comprehensive and detailed analysis of the multifaceted role of AR in breast cancer." (PMID 41590361, 2026). "Higher AR expression in ER-positive breast cancers is generally correlated with better clinical outcomes and a favorable response to endocrine therapies, such as selective estrogen receptor modulators (SERMs) and aromatase inhibitors." (PMID 40286049, 2025). "Additionally, AR signaling has been associated with the regulation of breast cancer cell proliferation, migration, and invasion, with some studies suggesting that androgens may have tumor-suppressive effects in certain subtypes of breast cancer, while promoting malignancy in others." (PMID 40286049, 2025). "A deeper understanding of the molecular mechanisms governing AR activity in breast cancer will be essential for the development of targeted therapies aimed at modulating AR function to improve patient outcomes." (PMID 40286049, 2025). "In our study, the AR expression rate was 73% among the HR-positive/HER2-negative breast cancer patient population." (PMID 40870508, 2025). "This study establishes BQ as a key modulator of DOX resistance in ER+ve breast cancer through an AR-CCRK-KU70 axis that enhances NHEJ-mediated DNA repair." (PMID 40940753, 2025). "The androgen receptor (AR) is expressed in over 70% of breast cancers, suggesting its potential as a novel biomarker and therapeutic target for breast cancer patients." (PMID 40870508, 2025). "AR in HR+ breast cancer correlates with a favorable prognosis, and AR agonism inhibits the progression of both endocrine-responsive and -refractory breast cancers." (PMID 40244377, 2025). "In estrogen receptor (ER)-positive breast cancer, the overexpression of the AR exerts its tumor-suppressive effect by competitively inhibiting ER signaling through genetic and non-genetic competition." (PMID 40729027, 2025). "Progression-free survival and overall survival (OS) were significantly prolonged in patients with early stage breast cancer who had high expression of AR." (PMID 40118451, 2025). "The BQ-AR-CCRK-KU70 axis represents a novel mechanism of DOX resistance in ER+ve breast cancer, suggesting AR or CCRK inhibition as a potential therapeutic strategy." (PMID 40940753, 2025). "We report new compounds that are able to impair the growth of sensitive and resistant ER+ breast cancer cells by acting as AIs, ER modulators and AR agonists, which is a therapeutic advantage over the current drugs applied in clinic." (PMID 39857947, 2025). "Although AR is overexpressed in 70–90% of all breast cancers, including up to 30% of TNBC, its contribution to TNBC aggressiveness and chemotherapy sensitivity remains controversial." (PMID 40150035, 2025). "Further research is needed to fully understand the impact of androgen-receptor expression on tumor initiation and progression in both human and canine breast cancer." (PMID 40286049, 2025). "The tumor‐homing peptide AR engineered at the tip of the phage facilitated selective breast cancer targeting." (PMID 39233557, 2025). "Two subtypes, Luminal Androgen Receptor and Molecular Apocrine Breast Cancers, are both defined by androgen signaling but identified through distinct transcriptomic classifiers." (PMID 41456038, 2025). "The CBP/EP300 BRD inhibitor FT-6876 reduced AR signaling and inhibited the growth of AR-dependent breast cancer models in vitro and in vivo." (PMID 40165290, 2025). "Androgen receptor (AR) activity has been shown to confer anastrozole resistance in ER+ve breast cancer, the effect being BQ-dependent." (PMID 40940753, 2025).
breast carcinoma (continued). "The results revealed that AR was positively correlated with SOX2-OT in the breast cancer populations (r = 0.317; p < 0.001)." (PMID 40118451, 2025). "A comparative analysis of androgen receptor (AR) expression in human breast cancer and canine mammary tumors offers a promising approach to understanding the molecular pathways shared between these two types of malignancies." (PMID 40286049, 2025). "The pro-oncogenic actions of androgen receptor-induced cell proliferation, cell migration, the inhibition of cell–cell adhesion, and cell growth, which promoted breast cancer metastasis." (PMID 40278313, 2025). "FOXA1 can facilitate the binding of ER and AR to their target genes, which is particularly important in luminal breast cancer." (PMID 40003882, 2025). "A new arylpyrazolopyrimidinone derivative was reported to exert a dual PDE5 and androgen receptor (AR) inhibitory activity that showed a significant cytotoxic effect on breast cancer cell lines." (PMID 39592536, 2025). "Apart from the ER, the AR is also expressed in breast cancer cells, and DHT has been shown to potently inhibit the E2-mediated stimulatory effect on cell proliferation." (PMID 39940958, 2025). "A systematic retrospective analysis found that AR is an independent prognostic factor for breast cancer." (PMID 40118451, 2025). "Studies in ER-positive and apocrine breast cancer cell lines identified that AR inhibits ER-induced transcription and proliferation effects by binding to EREs to prevent the binding of ER." (PMID 40023399, 2025). "Early-phase clinical trials exploring the use of anti-androgen agents, such as enzalutamide and bicalutamide, have shown promising results in AR-positive breast cancer subtypes, particularly those with a poor prognosis." (PMID 40286049, 2025). "A phase Ib/II TBCRC032 study has investigated the safety and effectiveness of the androgen receptor antagonist enzalutamide in combination with the PI3K inhibitor taselisib in patients with metastatic AR‐positive (≥10%) breast cancer, including TNBC." (PMID 40740483, 2025). "Studies have shown that AR-positive breast cancers tend to have a less aggressive phenotype, with slower tumor growth and a lower risk of metastasis." (PMID 40286049, 2025). "The mechanism of action of ARs in breast cancer involves a complex interplay between AR signaling and estrogen receptor (ER) signaling pathways." (PMID 40286049, 2025). "Enobosarm is a first‐in‐class oral SARM that targets the Androgen Receptor (AR), thus inhibiting the growth of AR‐positive, ER‐positive breast carcinoma cells." (PMID 40275985, 2025). "Invasive apocrine carcinoma (IAC) is a rare histologic subtype of breast carcinoma that commonly shows an ER/PR/HER2 triple negative phenotype with strong androgen receptor (AR) expression." (PMID 41245818, 2025). "One emerging area of research is the role of androgen receptor (AR) expression across breast cancer subtypes." (PMID 40734715, 2025). "In another study, the authors developed a multi-parametric MRI-based radiomics models to predict breast cancer molecular subtypes and androgen receptor (AR) expression." (PMID 41228202, 2025). "Androgen receptor (AR), a nuclear hormone receptor similar to estrogen receptor (ER), is expressed in 60% to 80% of breast cancer and 10% to 35% of TNBC patients." (PMID 40118451, 2025). "Background and Objectives: The effect of AR expression on prognosis in hormone receptor-positive her2-negative breast cancer is controversial." (PMID 40870508, 2025). "The similarities between canine mammary tumors and human breast cancer in terms of AR expression and its effects on tumor progression emphasize the importance of continued research into AR signaling pathways." (PMID 40286049, 2025). "The inclusion of ER-negative cell lines (e.g., BT-549, MDA-MB-231, MDA-MB-453) in our study, despite the focus on ER+ breast cancer, was intended to validate AR responsiveness to DHT across subtypes." (PMID 40940753, 2025).
breast carcinoma (continued). "This study elucidates the role of BQ323636.1 (BQ), a splice variant of NCOR2, in conferring doxorubicin (DOX) resistance in ER+ breast cancer through an AR-dependent mechanism." (PMID 40940753, 2025). "The interplay between AR and other key receptors, such as estrogen and progesterone receptors, is central to understanding its role in breast cancer." (PMID 40286049, 2025). "Androgen receptor (AR) is a nuclear steroid hormone receptor that is frequently expressed in breast cancer, particularly in ER-positive cases, where it is often considered a favorable prognostic marker." (PMID 39851328, 2025). "In this study, the expression rate of androgen receptor (AR) in the hormone receptor-positive/HER2-negative breast cancer patient population was 73%, which is consistent with values reported in the literature." (PMID 40870508, 2025). "The luminal androgen receptor (LAR) subtype of TNBC, which is characterized by high AR expression, shares some molecular features with luminal-type breast cancers." (PMID 39851328, 2025). "In breast cancer cells, synthetic androgens activate AR, upregulating ERβ expression and inhibiting growth." (PMID 40023399, 2025). "GNPDA1 and SLC25A16 play important roles in the BRCA1, BRCA2, and pro-oncogenic actions of the androgen receptor in breast cancer development." (PMID 40278313, 2025). "AR signaling can act as either a tumor suppressor or an oncogene, depending on the breast cancer subtype, the presence of co-receptors, and the specific molecular context within the tumor microenvironment." (PMID 40286049, 2025). "Several studies have explored the potential use of anti-androgens, such as enzalutamide and bicalutamide, to block AR signaling in various cancer types, including breast cancer." (PMID 40286049, 2025). "Like human breast cancers, canine mammary tumors exhibit a range of molecular profiles, with AR expression playing an important role in tumor progression, differentiation, and prognosis." (PMID 40286049, 2025). "Nevertheless, our study yielded results consistent with the literature, indicating that androgen receptor can be used as a therapeutic target in breast cancer, a mechanism explaining resistance to endocrine therapy, and a prognostic marker." (PMID 40870508, 2025). "Some evidence shows that AR and ER work synergistically to manifest breast cancer by upregulating kallikreins, known markers for breast cancer." (PMID 40023399, 2025). "The androgen receptor (AR) is a steroid nuclear receptor commonly expressed in HR+HER2− breast cancer, and SARMs act as either AR agonists or antagonists." (PMID 40244377, 2025). "Given the complex role of ARs in breast cancer, therapeutic strategies targeting AR are being actively investigated." (PMID 40286049, 2025). "The results of one meta-analysis showed that the AR-positive status was more frequently observed among ER-positive compared to ER-negative early breast cancers." (PMID 40150035, 2025). "AR is a member of the steroid hormone receptor family and is expressed in more than 70% of breast cancer patients." (PMID 40118451, 2025). "Androgen and estrogen action is mediated by steroid/nuclear receptor-transcription factors (AR and ERα/β) that are therapeutic targets for prostate and breast cancer." (PMID 38819630, 2025). "Given the high prevalence of AR (70–95%) in ER+ breast cancers and its context-dependent prognostic role, understanding the contribution of AR to DOX resistance is important." (PMID 40940753, 2025). "The annual protocol of the EORTC 10085/TBCRC/BIG/NABCG International Male Breast Cancer Program reports improved overall and recurrence-free survival in patients with highly ER-positive, PR-positive, and AR-positive disease." (PMID 41321964, 2025). "On the other hand, orteronel showed poor clinical activity as monotherapy in a phase II study (NCT01990209) in AR expressing advanced breast cancer including a TNBC cohort." (PMID 40003864, 2025).
breast carcinoma (continued). "Cell death increase was also observed in other ASS1-null cancer cells within the panel tested, including the SCLC cell lines DMS 114 and H69 AR and the breast cancer cell line MDAMB231." (PMID 39898973, 2025). "Our study is aimed at addressing these gaps by evaluating the expression of AR and TANs across different breast cancer subtypes, grades, and stages." (PMID 40734715, 2025). "In ER-negative (ER−) breast cancer, the activation of AR leads to the upregulation of Wnt and epidermal growth factor 2 (HER2) protumorigenic signaling pathway by increasing the transcription of Wnt family member 7B and epidermal growth factor 3 (HER3)." (PMID 40023399, 2025). "According to the NCCN guidelines, AR‐targeted therapy is recommended solely as a personalized therapeutic option for advanced breast cancer patients with AR‐positive tumors." (PMID 40703006, 2025). "AR, a member of the steroid hormone receptor (HR) family, is present in approximately 70%–80% of breast cancers but varies significantly depending on subtype." (PMID 40734715, 2025). "It acts as a coactivator of nuclear hormone receptors such as AR and ER, thereby promoting the progression of prostate and breast cancers by enhancing histone modifications and transcriptional activation at hormone-responsive elements." (PMID 40818609, 2025). "Understanding the mechanisms of action of ARs in human breast cancer is essential for the development of novel therapeutic strategies targeting AR signaling pathways." (PMID 40286049, 2025). "Context-specific factors likely modulate AR's role in breast cancer, as existing studies suggest AR's behavior is highly dependent on the surrounding tumor environment and associated oncogenic signals." (PMID 40734715, 2025). "In conclusion, the BQ-AR-CCRK-KU70 axis drives DOX resistance in ER+ breast cancer through NHEJ, providing a foundation for personalized therapies that combine AR/CCRK inhibitors with DOX." (PMID 40940753, 2025). "In some studies, AR activation has been shown to induce a growth-inhibitory effect in canine mammary tumor cell lines, especially in tumors that are estrogen receptor-positive." (PMID 40286049, 2025). "On the other hand, in canine mammary tumors, AR expression is less well-studied, but preliminary evidence suggests a potential role in tumor development and progression." (PMID 40286049, 2025). "Future research should aim to elucidate the significance of AR expression in both human and canine mammary tumors to further our understanding of these diseases." (PMID 40286049, 2025). "In conclusion, the comparative analysis of AR expression in human breast cancer and canine mammary tumors holds great potential for advancing our understanding of the molecular mechanisms driving breast cancer pathogenesis in both species." (PMID 40286049, 2025). "Collectively, these data indicate that GATA3 is a critical co-factor for AR action in ER+ and ER- breast cancer and facilitates AR-mediated tumor suppressor activity." (PMID 38317241, 2024). "AR has been receiving a lot of attention for its role in ER+ breast cancer development and, consequently, as a potential therapeutic target for this disease." (PMID 39338407, 2024). "While normal and non-neoplastic cells were resistant to YJ9069 (IC50 > 10,000 nM), androgen receptor (AR)-positive prostate and breast cancer cells were preferentially sensitive (IC50 < 500 nM)." (PMID 39353441, 2024). "Little is known about AR status in male breast cancer, but it is receiving increasing attention here as an additional therapeutic target." (PMID 37902839, 2024). "This has fundamentally limited the ability to define and differentiate AR action across breast cancer subtypes." (PMID 38317241, 2024).
breast carcinoma (continued). "Androgen receptor (AR) can serve as a new therapeutic target since it was shown to play a proliferative role in several breast cancer (BC) subtypes." (PMID 37902839, 2024). "Recently, a direct interaction of AR with GATA3 has been shown to regulate a luminal epithelial phenotype in breast cancer." (PMID 39273194, 2024). "The reason for these sex differences is unclear, but H2A.Z function is strongly intertwined with sex hormones in prostate and breast cancer cells, and its function is closely related to androgen receptor regulation in the brain." (PMID 38366138, 2024). "Using breast cancer cell lines, they also showed that AR was detected at 42% of estrogen-stimulated ER-binding sites on chromatin when both AR and ER were activated." (PMID 38339092, 2024). "Of note, the AR is also a tumor suppressive in AR and estrogen receptor positive breast cancer cells." (PMID 38902772, 2024). "This autoregulation displays a high degree of tissue specificity, as breast cancer cells show similar autorepression; whilst bone and postmenopausal endometrium display an inverted AR-mediated upregulation of AR transcription." (PMID 39088439, 2024). "It is well established that ER and AR signaling induces cell growth in certain breast cancer subtypes." (PMID 39684829, 2024). "In the context of ER- breast cancer, the expression of AR and its interaction with GATA3 likely promotes a more differentiated luminal phenotype, explaining why AR-ER- breast cancers represent the most aggressive, undifferentiated breast cancer subtype." (PMID 38317241, 2024). "In this study, we focused on ZAG as a candidate protein to regulate AR-dependent immune-regulatory mechanisms in the breast cancer microenvironment." (PMID 38349455, 2024). "On the other hand, a study by Hickey and colleagues demonstrated that AR behaves as a tumor suppressor in ERα-positive breast cancer." (PMID 38339092, 2024). "Recently, the role of the androgen receptor (AR) in breast cancer is gaining greater attention as a therapeutic target and as a prognostic biomarker." (PMID 38339092, 2024). "Its involvement in cancer progression, especially in breast cancer, makes AR a critical target for therapeutic intervention." (PMID 39769441, 2024). "In fact, there are some ongoing clinical trials with AR antagonists and AIs or anti-estrogens for breast cancer treatment." (PMID 39338407, 2024). "In breast cancer, AR IHC has been proposed as a tool for the detection of apocrine differentiation and metastases from triple-negative cancers." (PMID 38790919, 2024). "The exact role of the androgen receptor and its ligand androgens in breast cancer pathogenesis remains controversial." (PMID 39497884, 2024). "In the context of ER- breast cancer, AR activation inhibits proliferation of MFM-223 cells, but has variable proliferative effects on MDA-MB-453 cells." (PMID 38317241, 2024). "Recent research has shown that macrophages express AR and play key roles in various human diseases, including breast cancer." (PMID 39682229, 2024). "Recently, we reported that the benefit of RAD-140 (an AR agonist) and enzalutamide (Enz, a partial AR antagonist) in breast cancer cell lines was dependent on the ratio of AR to ER level." (PMID 38965614, 2024). "Paradoxically, the investigators also reported that the proliferation of most breast cancer cell lines was inhibited with AR antagonists." (PMID 39273194, 2024). "Successful targeting of the AR has also been reported in bladder cancer, salivary gland carcinoma, and breast cancer, where the AR is supposed to interact with estrogen receptor signaling." (PMID 38790919, 2024). "AR expression in CAFs within breast carcinoma tissues has also been confirmed through RT-PCR and immunohistochemistry using CAFs isolated from primary breast tumor biopsies." (PMID 39682229, 2024). "Meta-analyses of published data have been employed to assess the prognostic significance of the expression of AR in breast cancer." (PMID 38339092, 2024).